MMP8 (matrix metallopeptidase 8)
Diseases named in the same sentence as MMP8 in open-access papers (continued):
Sharing a sentence is not in itself a finding about the gene and the disease.
tumor (continued). "Matrix metalloproteinase-8 (MMP-8; neutrophil collagenase) is an important regulator of innate immunity that has oncosuppressive actions in numerous tumor types." (PMID 25848906, 2015). "The current study provides the first evidence from a spontaneous mouse tumor model for the tumor- and metastasis-suppressive functions of MMP-8." (PMID 25848906, 2015). "Throughout the 14 weeks of the model, tumor burden increased in homozygous Mmp8-null mice compared to Mmp8-wild-type and -heterozygote animals." (PMID 25848906, 2015). "Expression of MMP-8 by tumor cells reduces invasion and increases adhesion to type-I collagen and laminin matrices." (PMID 25848906, 2015). "The reduction of miR-21 expression by MMP-8 in turn leads to the inhibition of tumor growth and lung metastasis subsequently with a reduction of TGF-β signaling, thus indicating a new way for MMP-8 contribution to decrease tumor progression." (PMID 24578639, 2014). "Matrix metalloproteinase 8 (MMP-8) is a tumor-suppressive protease that cleaves numerous substrates, including matrix proteins and chemokines." (PMID 23632023, 2013). "This is particularly the case for MMP-8, which has been reported to suppress tumor formation or metastasis, depending on the model system." (PMID 23632023, 2013). "Of those, expression of MMP-8, -10, -12 and -27 is related to tumor grade since it is higher in analyzed G3 compared to G2 tissue samples." (PMID 19531263, 2009). "We found a trend of lower MMP1 levels with increasing tumour size (p = 0.07); and higher MMP8 levels with premenopausal status (p = 0.06) and NPI (p = 0.04)." (PMID 18366705, 2008). "A tumor protective role of a number of matrix degrading proteases, including MMP8 and MMP12, has been described." (PMID 18698413, 2008). "Traditionally, MMP8 was considered to promote tumour invasion and metastasis in accordance with the general view on MMPs in cancer." (PMID 18366705, 2008). "Further, we observed a weak positive correlation (rs = 0.16, p = 0.04) of plasma MMP8 with the Nottingham Prognostic Index which is calculated based on the tumour size, differentiation grade and lymph node status." (PMID 18366705, 2008). "Immune-related genes, such as chemokine (Cxcr2), C-type lectin (Clec4e), chemokine ligand (Cxcl3), tumor growth-related genes, galectin-7 (Lgals7), and matrix metallopeptidase 8 (Mmp8), were downregulated by colonization of B. plebeius in colon tissues of the mice exposed to AOM/DSS." (PMID 39804065, 2025). "This correlates with heightened expression of matrix metalloproteinase 8 (MMP8), a well-characterized antitumorigenic MMP, and a shift in the polarization of tumor-associated neutrophils (TANs) towards the antitumor N1 phenotype in the tumor microenvironment (TME)." (PMID 38937435, 2024). "A study among 141 PDAC patients showed a positive tumoral MMP8 stain, and a low plasma CRP level predicted a favorable prognosis; MMP8 expression in the tumor could be considered as an independent positive prognostic factor for PDAC33." (PMID 37821678, 2023). "Furthermore, the expression of EMT genes and oncogenes, including Mmp3, Mmp7, Mmp8, Fn1, Vim, Foxc2, Ctnnb1, Lgr5, Axin2, cMyc, Ccnd1, and Yap1, was significantly high in the tumor of cohoused Nlrp12–/– compared with WT mice." (PMID 37581937, 2023). "In the case of MMP-8, it can directly inhibit tumor metastasis." (PMID 37895400, 2023). "Furthermore, the tumor levels of YKL-40 correlated significantly with those of MMP-8, IL-17, and PD-L1 levels." (PMID 37185706, 2023). "Furthermore, MMPs have pleiotropic activity, for example, MMP-8 has both pro-tumor and anti-tumor functions." (PMID 37560476, 2023). "Matrix metalloproteinase 8 (MMP8) was considered as a tumor promoter in various tumors." (PMID 35884594, 2022). "Additionally, neutrophils promote tumor motility, migration and invasion via the release of neutrophil elastase, cathepsin G, proteinase 3, MMP8 and MMP9." (PMID 35682709, 2022).
tumor (continued). "The absence of tumour-associated MMP-8-positive PMNs together with an elevated CRP level associated with an unfavourable prognosis (HR = 2.99; 95% CI 1.60–5.59; p = 0.001) compared to a positive PMN score and a low CRP level." (PMID 35328734, 2022). "MMP-1, MMP-2, MMP-8, MMP-11, and MMP-13 are implicated in the regulation of tumor cell migration." (PMID 36776395, 2022). "MMP-8 affects the immune response to tumor and helps to resolve necrosis, which is positively related to the degree of primary tumor necrosis and blood neutrophil count, as well as negatively correlated with destructive inflammatory infiltration and Crohn’s-like lymphoid reaction." (PMID 36776395, 2022). "One such tumor suppressor was the extracellular matrix-modifying enzyme MMP8." (PMID 33235291, 2021). "MMP‐8 is thought to play a role in inflammation and different tumor processes." (PMID 32985799, 2021). "Our finding supports a novel tumour-protective molecular mechanism of MMP8 in OTSCC, which could apply to other diseases as well." (PMID 34059618, 2021). "Therefore, postulating the exact mechanisms on how MMP8 modulates tumour development is less accurate." (PMID 34356991, 2021). "This might reflect the fact that male tumors were often larger in size, as MMP‐9 is needed for tissue destruction while the tumor is still growing, and that MMP‐8, and ‐9 may have mutual inducers in wound healing and related inflammation." (PMID 32985799, 2021). "In conclusion, to our estimate, inflammatory cells expressing MMP‐8 and ‐9 might promote tumor growth by providing extracellular degradation or cytokine activation." (PMID 32985799, 2021). "In addition, due to the disease relevance of Cu(II) in cancer where it is found that the concentration of Cu(II) is elevated in tumor tissues, focus has also been given to the effects of Cu(II) cofactor on the structures of the MMP8 protein." (PMID 33275641, 2020). "It is now known that the MMPs may play a protective role in tumour progression including MMP-8 and indeed much broader roles in inflammation than previously appreciated, many of which are protective." (PMID 32466182, 2020). "However, to evaluate the overall function of MMP8 in various steps of cancer progression, the tumor-promoting mechanisms of this multifunctional enzyme should also be studied." (PMID 31514474, 2019). "However, MMP-8 expression positivity was observed in the inflammatory polymorphonuclear leukocytes adjacent to the tumor in the majority (n = 76, 91.6%) of samples." (PMID 31240326, 2019). "Other genes were also found to be up-regulated, including Bmp7, which antagonizes transforming growth factor β1 (TGFβ1)-mediated fibrosis through suppressing epithelial-mesenchymal transition, and Mmp8, which prevents metastasis formation through the modulation of tumor cell adhesion and invasion." (PMID 30621584, 2019). "Additionally, MMP8 was shown to be present in the OSCC tumor interstitial fluid in samples collected during surgery and analyzed by mass spectrometry." (PMID 31514474, 2019). "Based on the studies, these cancers might benefit from having a MMP8-inactivating SNP suggesting that MMP8 is a tumor-protective factor in them." (PMID 31514474, 2019). "However, MMP8 expression has also been shown to increase in highly vascularized tissues such as tumor and placenta and this protease is generally regarded as a proangiogenic factor." (PMID 31514474, 2019). "Additionally, matrix metalloproteinases (e.g., MMP-8 and MMP-9) derived from tumor associated neutrophils (TAN) further contribute to the immunosuppressive nature of the tumor microenvironment." (PMID 30400571, 2018). "For example, the combination of Immunoscore and serum MMP-8, reflecting both anti-tumour immune response and systemic inflammation, achieved good discrimination ability in ROC analysis and both parameters significantly contributed to the multivariate Cox regression model of CSS." (PMID 29808017, 2018).
tumor (continued). "In addition, arazyme induced the production of protease-specific IgGs that cross-reacted with tumor MMP-8." (PMID 24788523, 2014). "Neutrophils may also exert their antitumor activities by expressing and secreting MMP-8, which is mainly produced by neutrophils and has been postulated as a tumor suppressor." (PMID 24578639, 2014). "We suggest that the antitumor activity of arazyme in a preclinical model may be due to a direct cytostatic activity of the protease in combination with the elicited anti-protease antibody, which cross-reacts with MMP-8 produced by tumor cells." (PMID 24788523, 2014). "Several studies have demonstrated tumor- or metastasis-suppressive activities of MMP-8." (PMID 23632023, 2013). "Furthermore, co-injection of MMP-8-expressing Ads in combination with wild-type Ads resulted in reduced tumor cell growth and collagen expression within areas of virus-induced necrosis compared with wild-type Ad given together with a control Ad vector." (PMID 23898462, 2013). "Importantly, bone marrow transplantation assays in those mutant mice revealed that MMP8-producing neutrophils are sufficient to rescue the anti-tumor protection conferred by this enzyme." (PMID 22822400, 2012). "It has been reported that BQ may accelerate tumor migration by stimulating MMP-8 expression through MEK pathway in at least some carcinomas of the upper aerodigestive tract." (PMID 22912735, 2012). "Patients with tumours lacking MMP-8 expression in cancer cells had a relative SCC mortality rate of 3.70 (95% CI 1.04–12.5) compared to patients with some MMP-8 positive immunostaining, when adjusted for age, sex, and stage of tumour (TNM) by the proportional hazards model." (PMID 18253113, 2008). "If we assume, as for MMP1, that the higher plasma MMP8 levels reflect a lower expression in the tumour tissue; then the positive relation of plasma MMP8 with premenopausal status, and as such earlier onset, supports the notion of a protective role of MMP8 in cancer." (PMID 18366705, 2008). "Indeed, MMP-8 modulates the innate immune response induced by carcinogens leading to a protective role in preventing tumour progression." (PMID 17375198, 2007). "The results we obtained may indicate that MMP-8 is involved in the pathogenesis of OC; however, its activity is limited to the tumor lesion itself—the reason for which may be the lower concentrations of MMP-8 in the peripheral blood of OC patients than in BL and HS." (PMID 39682156, 2024). "In addition, we find that matrix metalloprotease expression (e.g. MMP8) is significantly enhanced with the immunotherapy treatments including aPD-1 and aCD40 and the enhanced expression is maintained in the distant tumor for the combination of ablation and aPD-1 or CP4." (PMID 36451859, 2022). "Thus, taking into consideration these data, we may speculate that in BPV-2 positive fibropapillomas, overexpression of MMP-8 may interfere with tumor further development." (PMID 36713871, 2022). "Despite this, several reports have suggested that MMP8 might have anti-tumoral properties, by reducing the migratory activity of cancer cells and increasing cell attachment to extracellular matrixes within the tumour." (PMID 34356991, 2021). "MMP8 might have protective roles over tumour growth and spread in our body." (PMID 34356991, 2021). "However, the role of MMP-8 in tumor progression is controversial." (PMID 31010242, 2019). "Moreover, more detailed analyses of serum MMP-8 levels in CRC in relation to different types of tumour-infiltrating immune cells and systemic inflammatory markers could improve our understanding of tumour-related inflammatory reactions." (PMID 29808017, 2018). "However understanding the mechanism by which MMP-8 mediates this anti-tumour role is incomplete." (PMID 28330493, 2017). "However, neutrophils-derived MMP-8 was regarded as playing a protective role in tumor progression." (PMID 27446967, 2016).
tumor (continued). "MMP-8 may control the invasion potential of tumor cells by modulating cell adhesion." (PMID 25352026, 2015). "In skin carcinogenesis or excisional wound repair, Mmp8-null mice show delayed neutrophil recruitment at early stages, but there is persistent neutrophil accumulation at later times, leading to a chronic inflammatory milieu that enhances tumor formation and impairs wound repair." (PMID 25848906, 2015). "In the MMTV-PyMT model we found no deficit in neutrophil accumulation at early-mid stages of tumor development (6 and 8 weeks), but by 10 weeks the neutrophil count in sections of wild-type tumors had declined, whereas levels remained elevated for tumors in both Mmp8-null and -heterozygote mice." (PMID 25848906, 2015). "Thus, MMP-8 may participate in and orchestrate multiple events in the tumor microenvironment during the stages of tumor progression." (PMID 25848906, 2015). "Interestingly, an RNA interference screen has identified MMP-8 as a protein that interacts with and modifies the activity of β1 integrin, which may be the basis for its effects on tumor cell adhesion." (PMID 25848906, 2015). "The observed effects of cannabinoids on AGS cells were also studied on gastric xenografts, decreasing the tumor volume by 30% and decreasing invasion (MMP2/MMP9/MMP8)." (PMID 40076652, 2025). "Mmp8 produced by PMN-MDSCs enhances metastasis by promoting extravasation and engraftment of circulating tumor cells." (PMID 41282257, 2025). "With the continuous development of tumors, anti‐inflammatory N2‐type increases the secretion of matrix metalloproteinase 8 or 9 (MMP8, MMP9), IL‐1β and IL‐6 to promote tumor invasiveness." (PMID 38585234, 2024). "It shows how the levels of IL-1, 2, 4, 6, 17, MMP-8 and HSP-90 remained significantly different among one two types of tumours." (PMID 38956273, 2024). "Neutrophils secrete matrix metalloproteinase-8 (MMP-8), vascular endothelial growth factor (VEGF), and neutrophil elastase, which enhance tumor growth, angiogenesis, and suppression of T cells activity in the TME." (PMID 39464714, 2024). "The six HCC TAN clusters; MMP8+, APOA2+, CD74+, IFIT1+, SPP1+ and CCL4+ can be characterised by predicted function and role in tumour development." (PMID 37534829, 2023). "The S100A12+, ISG15+ and TXNIP+ subtypes are found in peripheral blood, the ELL2+ and PTGS2+ mainly in adjacent liver and the MMP8+, APOA2+, CD74+, IFIT1+, SPP1+ and CCL4+ predominantly located in the tumour." (PMID 37534829, 2023). "In this study, we aimed to examine the expression of MMP-8 in PDAC tissue and the amount of MMP-8-positive polymorphonuclear cells (PMNs) in the tumour area." (PMID 35328734, 2022). "In primary tumor tissues, they have previously been shown to support tumor growth, invasion, and angiogenesis possibly due to release of ECM remodeling enzymes such as MMP-8, MMP-9, elastase, and cathepsin G." (PMID 35954395, 2022). "Although MMP-8 immunoexpression in the tumour seems to represent an independent prognostic factor, the combination of the CRP level and MMP-8 expression offers more precise prognostic information." (PMID 35328734, 2022). "However, MMP-8 may directly inhibit tumor metastasis in tumor cells." (PMID 36776395, 2022). "Interestingly, when MMP-8 enzyme was analyzed, we revealed for the first time predominantly a moderate cytoplasmic and perinuclear immunoreactivity, whilst the overexpression in tumor sample comparing to normal skin tissue was confirmed with western blot analysis." (PMID 36713871, 2022). "Neutrophils secrete proangiogenic cytokines, which include IL-8, MMP-9, MMP-8, and VEGF, which are known to contribute to tumor angiogenesis and progression." (PMID 34446028, 2021). "While N1 TANs exert anti-tumor activity through ADCC and proinflammatory factors production, such as IFN-γand MMP-8, in the innate immune response, N2 TANs promote tumor growth." (PMID 34692696, 2021).
tumor (continued). "Regarding the MMP8 detection in skin, it is highly expressed in the course of skin inflammatory processes, conventionally attributed to production/secretion from polymorphonuclear neutrophils (PMN), suggesting that MMP8 has a role in dermic destruction." (PMID 33255937, 2020). "Doxycycline treatment downregulated the levels of MMP-2, MMP-8, MMP-9 and NF-kB in a dose-dependent manner, which represents another important molecular pattern that restricts tumour cell proliferation, invasion and angiogenesis." (PMID 32377334, 2020). "Either Sal-B or cisplatin treatment decreased tumor tissue levels of tumor necrosis factor (TNF-α), matrix metalloproteinase-8 (MMP-8), and Cyclin D1 in ESC treated mice." (PMID 31726654, 2019). "In their studies, MMP8 cleaved decorin, which inhibits TGF-β1: The subsequent downregulation of miR-21 expression led to activation of known tumor suppressors such as programmed cell death 4 (PDCD4)." (PMID 31514474, 2019). "Of all these enzymes, uPA, MMP-8 and -9 as well as several cathepsins were expressed in SCLC tumor lines, the two SCLC CTCs and conditioned macrophages in our screening experiments." (PMID 30669448, 2019). "To evaluate their role as prognostic factors, we studied serum levels of MMP-8 and TIMP-1 and their expression in OPSCC tumor tissue." (PMID 31240326, 2019). "MMP8, ITGB2, and CLDN1 are well-studied proteins that have evolved with tumor cell’s higher ability for invasion." (PMID 29520031, 2018). "The three proteins (MMP-8, TIMP-4 and EGF) that following a decrease during tumor inhibition also showed evidence for an increase during progression are involved in cancer cell survival, proliferation and migration." (PMID 30592740, 2018). "A significant decrease in tumour invasion was observed for MDA MD 231 and SUM159 cells co-cultured with MMP-8 WT over-expressing β6-1089 compared to empty vector and MMP-8 EA, suggesting that MMP-8 contributes to MEC invasion-suppressor effect." (PMID 28330493, 2017). "Other pro-tumorigenic functions of TAN have been reported, such as tumor cell invasion via secretion of elastases, MMP8, MMP9 and cathepsin G and tumor cell proliferation via COX-2-dependent prostaglandin E2 synthesis." (PMID 27259252, 2016). "The mRNA expressions of TGFβ1, MMP8 (matrix metalloproteinase 8), and LTF (lactoferrin), which all show tumor suppressing ability, were significantly increased in Rheb1Δ/Δ GFP+ cells compared with the control." (PMID 27071307, 2016). "Despite the pro-tumorigenic function of certain metalloproteinases, recent studies have shown that other members of these families, such as MMP8 or MMP11, have a protective role against tumor growth and metastasis in animal models." (PMID 22822400, 2012). "Notably, we observed an influence of TIMP1, demonstrating a positive correlation with MMP8, MMP9, and MMP10 in tumor samples." (PMID 38474106, 2024). "Finally, immature TANs that are likely to play anti-tumour roles were identified in PDAC (TAN-3), gastric cancer (tsNeu1) and HCC (MMP8+)." (PMID 37534829, 2023). "Finally, the MMP8+ and APOA2+ TANs expressed lower levels of PD-L1, correlated with a better prognosis and were therefore predicted to play an anti-tumour role in HCC." (PMID 37534829, 2023). "MMP8, like TGFβ/BMP, has many nuanced and context‐dependent roles that may be both tumor promoting and or suppressive, a context that may be important to the distinct process a tumor cell is attempting to achieve in a specific microenvironment." (PMID 36054271, 2023). "Other neutrophil-derived factors, such as granules containing neutrophil elastase (NE), neutrophil collagenase (or MMP8), and gelatinase B (or MMP9) can remodel the ECM in the TME or act directly on tumor cells themselves to boost tumor proliferation and invasion." (PMID 37398649, 2023).